RN7SL292P (RNA, 7SL, cytoplasmic 292, pseudogene)
Gene: Miscellaneous RNA gene on chromosome 7 (51,716,657 to 51,716,922, forward strand). Ensembl gene ENSG00000242650.
Homologues: Orthologues: chimpanzee Metazoa_SRP (99% identical), macaque Metazoa_SRP (80% identical). Paralogues in human: RN7SL1 (82% identical), RN7SL2 (82% identical), RN7SL3 (81% identical), RN7SL451P (81% identical), RN7SL567P (80% identical), RN7SL507P (80% identical), RN7SL712P (80% identical), RN7SL664P (80% identical), RN7SL300P (79% identical), RN7SL543P (79% identical), RN7SL769P (79% identical), RN7SL408P (79% identical), and 707 more.